CDKN2A (cyclin dependent kinase inhibitor 2A)
Diseases named in the same sentence as CDKN2A in open-access papers (continued):
Sharing a sentence is not in itself a finding about the gene and the disease.
lung carcinoma (continued). "Methylation events in plasma, specifically in CDKN2A, MGMT and RASSF1A, as well as in peripheral blood leukocytes and lymphocytes, are promising less invasive sites for assessing lung cancer risk through measuring DNA methylation differences." (PMID 23870182, 2013). "Epigenetic inactivation of tumor-suppressor genes, such as RASSF1A and CDKN2A (p16) has been observed in lung cancer patients exposed to asbestos." (PMID 23173984, 2012). "Inactivation of CDKN2A by DNA hypermethylation is now thought to be one of the earliest events during lung cancer development (and references therein) and is observed in hyperplasia and carcinoma in situ." (PMID 21731750, 2011). "The inhibitory effects of p16INK4a, p14ARF and p12 were studied in the human lung cancer cell line A549 which lacks the CDKN2A locus." (PMID 20565749, 2010). "Aberrant methylation of p16INK4a, FHIT, APC, MLH1, RASSF1, CDKN2A, and DAPK has been associated with lung cancer stage, metastasis, and an increased risk of recurrence after therapy." (PMID 18834524, 2008). "CDKN2A is one of the first tumor suppressor genes found to be methylated in a variety of cancers, including lung cancer." (PMID 17967182, 2007). "Lung cancer diagnosed as CDKN2A mutant is closely connected." (PMID 38206516, 2024). "Moreover, we found an inverse correlation between SIRT7 mRNA expression and CDKN2A protein levels in human lung cancers." (PMID 38870055, 2024). "Hence, it is important to diagnose and treat lung cancer early in individuals with homozygous deletion of CDKN2A." (PMID 39323996, 2024). "Notably, CDKN2A emerges as a promising candidate for a lung cancer biomarker, serving as an intersecting gene between differentially expressed genes and hub genes." (PMID 39734333, 2024). "Besides, the co-occurrence of deletion of CDKN2A and mutations of EGFR generally indicated poor treatment response to EGFR-TKIs in lung cancer." (PMID 36906568, 2023). "Inactivation of the cyclin-dependent kinase inhibitor 2A (CDKN2A) gene is considerably more frequent in squamous cell lung cancer (SqCLC) than in other subtypes of lung cancer and may be a promising target for this histology." (PMID 36835617, 2023). "Additionally, CDKN2A/B genes, a set of recognized lung cancer suppressor genes, copy number amplification was observed in M1, M3, and M4 BMs of Case 3, while no aberrations were found in the primary tumor and M2." (PMID 37384291, 2023). "This CDR sequence is the same as the CDKN2A deletion fragment in the HCC193 lung cancer cell line." (PMID 36531022, 2022). "In the old lung cancer group, there were genes significantly concurrent with actionable driver genes (CDKN2A, NF1): FAT1, LRP1B, ARID2 with CDKN2A; EPHB1 with NF1, and genes significantly exclusive with actionable driver genes (EGFR, KRAS): MLL2, STK11, KRAS with EGFR." (PMID 35096611, 2021). "In addition, methylation and, consequently, reduced protein expression of the CDKN2A has been demonstrated in lung cancer." (PMID 32648197, 2021).
lung carcinoma (continued). "In this case, Cyclin Dependent Kinase Inhibitor 2A (CDKN2A, OMIM association number 600160), the essential cell cycle regulating factor, is increasingly recognized to be involved in the pathological process of lung cancer." (PMID 33155773, 2020). "Our study consolidated the involvement of CDKN2A‐MTAP signaling in the context of lung cancer." (PMID 33155773, 2020). "Therefore, our data clearly suggested that MTAP predominantly mediated the tumor suppressor roles of CDKN2A in lung cancer." (PMID 33155773, 2020). "The study highlighted the importance of CDKN2A‐MTAP signaling in lung cancer." (PMID 33155773, 2020). "Along with epigenetic mechanisms, the biallelic inactivation of CDKN2A might heavily contribute to lung cancer incidence." (PMID 33155773, 2020). "In view of the complex regulatory network involved in cell cycle control elicited by CDKN2A deficiency, we hypothesized that MTAP might function indirectly and at the downstream of CDKN2A in lung cancer." (PMID 33155773, 2020). "In addition, genomic deletion spanning CDKN2A in lung cancer patients has been increasingly acknowledged." (PMID 33155773, 2020). "Work on identifying CDKN2A, as well as MGMT, as a measure of cancer risk and diagnosis was expanded in a 21-patient study of matched sputum and squamous cell carcinoma (SCC) samples as well as sputum samples from 32 patients evaluated for possible lung cancer." (PMID 23870182, 2013). "Our research is the first to show that, although all three transcripts of the CDKN2A gene can suppress the growth of lung cancer cells with an inactivated CDKN2A locus, they have different effects, with the growth inhibitory effect of p16INK4a being the strongest." (PMID 20565749, 2010). "CDKN2A/B loss might have negative prognostic and predictive value for lung cancer with immunotherapy, as reported by others as well." (PMID 36230855, 2022). "However, how CDKN2A regulates cuproptosis in lung cancer remains to be elucidated." (PMID 36712848, 2022). "Therefore, we hypothesized that CDKN2A/B should be considered in the management of clinical lung cancer." (PMID 35253368, 2022). "We found that the methylation status of the cyclin-dependent kinase inhibitor 2A (P16), Ras association domain family 1 isoform (RASSF1A), adenomatous polyposis coli (APC) and short stature homeobox 2 (SHOX2) genes was significantly correlated with lung cancer in bronchial aspirates." (PMID 28977861, 2017). "It suggested that an activation of the EGFR/PI3K/AKT/mTOR pathway could be linked to CDKN2A homozygous deletion in lung cancer regardless of smoking status." (PMID 18549475, 2008). "In lung cancer, patients with co-occurring CDKN2A, CDKN2B and IFN-I cluster deletion display shorter survival as compared with the ones carrying only deletion of CDKN2A." (PMID 40877968, 2025). "Epigenetic Indicators for Early Detection of Lung Cancer: Hypermethylation of genes like RARB, CDKN2A, and MGMT have emerged as promising biomarkers for lung cancer early detection, prognosis, and prediction of therapeutic response." (PMID 39982247, 2025).
lung carcinoma (continued). "The findings established that the mRNA expressions of CDKN2A and CDKN1A were significantly elevated in lung cancer cells treated with H2O2, and β-galactosidase staining was more intense." (PMID 39769336, 2024). "Therefore, CDKN2A may play a crucial role in inhibiting the progression from COPD into lung cancer." (PMID 37801050, 2023). "In clinical practice, many of these DMRs have the potential to predict disease progression, including in patients with stage IV lung cancer (SHOX2, RARB/RASSF1A, RARB, RASSF1A/APC, DCLK1, BRMS1, SOX17, SFN, CHFR, and APC/RASSF1A/CDH13/CDKN2A)." (PMID 36765815, 2023). "The usefulness of methylation signatures in the ctDNA of lung cancer was demonstrated in the serum of 200 patients by identifying hypermethylated promoter regions of tumor suppressor genes (MGMT, CDKN2A, INK4A, RASSF1A, DAPK, and RARB." (PMID 36765815, 2023). "By systematically analyzing the genetic alterations of 10 cuproptosis-related genes in lung adenocarcinoma, we found that CDKN2A, DLAT, LIAS, PDHA1, FDX1, GLS, and MTF1 were differentially expressed between lung cancer tissues and adjacent tissues." (PMID 36712848, 2022). "Similar to other types of lung cancer, amplifications or deletions of genes in the cell-cycle pathway (CCND1, CDKN2A, and RB1) were frequently identified in PSC." (PMID 32985499, 2020). "Especially, the identified genes EGFR, CDKN2A, ERBB2, RB1, and CDK4 were significantly enriched for non‐small cell lung cancer, demonstrating that UniCovEx accurately identified the cancer‐related gene modules." (PMID 30828525, 2019). "Previous genome analysis using SNP Arrays also showed CDKN2A homozygous deletions and CCNE1 amplifications in lung cancers." (PMID 18549475, 2008). "The ability of the top four candidates, CDKN2A EX2, CDX2, HOXA1 and OPCML (all p < 1 × 10-9), to individually identify lung cancer samples was next evaluated." (PMID 17967182, 2007). "CDKN2A/B, STK11, and KEAP1 had a high frequency of alterations in lung cancer BMs cases." (PMID 37384291, 2023). "In addition to CDKN2A, genes, including DLD, LIPT1, GLS, PDHB, and PDHA1, also have significant CNVs, indicating the heterogeneity of lung cancer tissue." (PMID 36712848, 2022).
lung carcinoma (continued). "Upon NUPR1 depletion, proteins such as CDKN2A, CDKN1A, and CDKN1B, which directly regulate cell cycle progression, are involved in the NUPR1-mediated autolysosomal process, which is consistent with our previous observation in lung cancer cells." (PMID 33542201, 2021). "Three of them (RASSF1A, CDKN2A, and DLEC1) were found only in lung cancer patients." (PMID 31752198, 2019). "The expression of CCNE1, CDKN1A (p21) and CDKN2A (p16) either did not appear to change or did not change in a similar direction in all 3 lung cancer cell lines as a function of BRG1 expression (data not shown)." (PMID 28105458, 2016). "These numbers suggest that if methylated plasma CDKN2A is to be useful in detecting lung cancer, it will likely be as part of a biomarker panel rather than as a single gene." (PMID 25988180, 2015). "Despite the small numbers in these rare lung cancer subtypes, SNV calling using the OncoMap database revealed previously undescribed SNV in FGFR1, CDKN2A, RB1, JAK3, and CTNNB1 for the large-cell type, a BRAF mutation for carcinoid, and an AKT1 mutation for adenosquamous carcinoma." (PMID 26076459, 2015). "The detection of CDKN2A methylation in a high fraction of lung cancer patient plasma samples bodes well for its application to non-invasive detection." (PMID 17967182, 2007). "Moreover, qPCR analysis revealed that overexpression of SLC16A4 upregulated the expression levels of CDKN1A and CDKN2A in A549 and H1299 cells, suggesting that SLC16A4 may suppress lung cancer cell proliferation by regulating the cell cycle." (PMID 40867526, 2025). "A third recent study reported that 9p21.3 loss (as assessed by CDKN2A, CDKN2B plus MTAP) was associated with poor survival after anti-PD-1 monotherapy but not in ICT–chemotherapy combination treated patients with nonsquamous lung cancer." (PMID 36395141, 2022). "Analysis indicated that CDKN2A, FAT1, MSH6, ARID1A, KEAP1, NF1, and SMAD4 mutation was more recurrent in patients with ERBB2 SNV/indels within the kinase domain compared with non-kinase domain in lung cancer." (PMID 35911441, 2022). "In this study, expressions of p16INK4 RB1, and CDKN2A copy number variances (CNV) in the tumor cells were assessed by immunohistochemistry and fluorescence in situ hybridization (FISH), respectively, in 73 nonsmall cell lung cancer (NSCLC) with known 5-year survivals." (PMID 22619677, 2012). "However, CDKN2A hypermethylation has previously been characterized as an early event in lung carcinogenesis, and hypermethylation of CDKN2A has been commonly detected in sputum samples from heavy smokers without lung cancer." (PMID 21577262, 2011). "One molecular mechanism possibly related to rapid tumor growth and the lack of response to brigatinib was the CDKN2A deletion detected in the third tumor rebiopsy, which promotes lung cancer progression and also impairs TKI responses in the similar constellation of EGFR-mutated lung cancer." (PMID 36207130, 2022). "Almost half (48.4%) of our lung cancer patients had lung squamous cell carcinoma (SCC), which is often perceived to lack molecular targets, however our results suggest that KRAS, PIK3CA, PTPN11 and CDKN2A, in particular, could potentially be actionable targets in lung SCC." (PMID 32087721, 2020).
lung carcinoma (continued). "Cyclin-dependent kinase inhibitor 2A (CDKN2A) is an essential cell cycle regulating factor, and a study found that the absence of CDKN2A promoted the progression of lung cancer and that it was correlated with poor survival." (PMID 35918384, 2022). "The methylation levels of eight genes (CALCA, HOXA9, RASSF1A, CDKN2A, DLEC1, CDH13, PITX2, and WT1) in ctDNA were significantly higher in lung cancer patients than in non-lung cancer patients." (PMID 31752198, 2019). "RB1 expression was mostly associated with a wild-type (wt) exon mutation status and its functionality in YAP1-positive cell lines was suggested by decreased or absent CDKN2A/2B expression, previously shown as an alternate mechanism to disable the RB1 pathway in lung cancer." (PMID 29088741, 2017). "RARβ, CDKN2A, DAPK, RASSF1A and MGMT were examined, and the analysis showed that a patient having methylation of just one gene had an odds ratio of 5.08, meaning they were approximately five times likely to have lung cancer than patients without any methylated genes." (PMID 23870182, 2013).